TNF (tumor necrosis factor)
Diseases named in the same sentence as TNF in open-access papers (continued):
Sharing a sentence is not in itself a finding about the gene and the disease.
autoimmune disease (continued). "Exacerbations of autoimmune diseases underanti TNF therapy was attributed to anti-inflammatory effects of TNF linked to theinhibition of IL-12p40 and IL-23 via TNFR1 on macrophages and dendritic cells." (PMID 26931771, 2016). "This review summarizes the data related to the association between TNF-α gene and its receptor polymorphisms, and the development of autoimmune diseases." (PMID 27652081, 2016). "In this article, we review the association between the genetic polymorphisms in TNF-α and the development of autoimmune diseases, and the relation between these polymorphisms and TNF-α expression." (PMID 27652081, 2016). "It has also been reported that nitration of EGF and TNFα makes these molecules strongly immunogenic, and that the presence of nitrotyrosine-modified proteins is associated with several autoimmune diseases." (PMID 26700624, 2016). "This case is reported to tell physicians to be cautious when using anti-TNF-α in patients with family history of MS and to reconsider the risk of MS in patients with autoimmune diseases." (PMID 27840642, 2016). "Glial fibrillary acidic protein (GFAP) has been shown to be upregulated in autoimmune diseases where TNFα and IL-1ßwere overexpressed, causing glial scarring as the astrocytes interact with neural injuries." (PMID 26648846, 2015). "Pro-inflammatory cells expressing tumor necrosis factor (TNF) and interleukin 17 (IL-17) cytokines have been strongly associated with disease development in AS, and other autoimmune diseases including PsA, RA, IBD and multiple sclerosis (MS)." (PMID 26125554, 2015). "The blockage of TNF-α causes the exacerbation or prolongation of preexisting autoimmune diseases, such as multiple sclerosis." (PMID 24600322, 2014). "TNF-α-308G>A (rs1800629) SNP has increased susceptibility to many kinds of tumors and autoimmune diseases, such as hepatocellular carcinoma, myeloma, lymphoma, ulcerative colitis, and Crohn’s disease." (PMID 24857911, 2014). "Polymorphism in the TNF-α promoter region has been shown to play an important role in the development of autoimmune diseases and several infections like HBV, HCV, leishmaniasis, etc.." (PMID 24837009, 2014). "Overexpression of tumor necrosis factor alpha (TNFA), a pro-inflammatory cytokine, has been implicated in autoimmune diseases and cancers associated with an inflammatory component." (PMID 24651674, 2014). "The critical role of TNF-α in development of many inflammatory and autoimmune diseases has encouraged researchers to pursue the influence of different TNF-α gene polymorphisms on development of some diseases including T1DM by a series of association studies." (PMID 24693923, 2014). "The 308 G/A polymorphism of TNF-α which leads to elevated TNF-α levels is known to have an important impact on the development of autoimmunity diseases, metabolic syndromes, cancers, and psychiatric disorders." (PMID 24891849, 2014). "TNF is well known to cause inflammatory reactions such as tissue injury in autoimmune diseases mainly by activation of TNF receptor type 1 (TNFR1)." (PMID 25400932, 2014). "TNF is a key cytokine in the inflammatory response and variations in expression of TNF have been implicated in many autoimmune diseases." (PMID 23961418, 2013). "Counterintuitive were observations that TNF blockade can be associated with development of inflammatory and autoimmune diseases, indicating a highly complex regulation of TNF action in vivo." (PMID 23977237, 2013). "Tumor necrosis factor (TNF)-α is a proinflammatory cytokine strongly implicated in the pathogenesis of autoimmune disease." (PMID 23522744, 2013). "The administration of methotrexate or TNF-alpha inhibitors for autoimmune disease is associated with a higher risk of PCP than other treatments." (PMID 24289285, 2013).
autoimmune disease (continued). "MS is an autoimmune disease whose pathology involves many of the same inflammatory mediators (tumor necrosis factor alpha (TNFα)) that are also commonly associated with the development of chronic pain syndromes such as NPP." (PMID 24175290, 2013). "Recently, genetic variants of the TNF gene have drawn increasing interest in the etiology of several autoimmune diseases." (PMID 24049437, 2013). "TNF-α and their receptors have been implicated in the pathogenesis of diverse autoimmune diseases with special interest in their polymorphisms." (PMID 22482039, 2012). "Polymorphism of TNF-α promoter region has been shown to play a role in the development of autoimmune diseases and several infections like malaria, leishmaniasis, hepatitis B virus, hepatitis C virus, human papiloma virus etc.." (PMID 22276993, 2012). "The less common −308A allele is strongly associated with the MHC haplotype HLA-A1-B8 and DR3, which is in turn associated with high TNF-α production and autoimmune disease." (PMID 23133455, 2012). "In simple terms, IFN-α is proposed as the primary pathogenic cytokine in ‘systemic’ autoimmune diseases, whereas TNF-α is believed to be the more pathogenic cytokine in organ-specific autoimmune diseases." (PMID 22454752, 2011). "Despite the therapeutic utility of IFN-α and TNF-α antagonists in human diseases, these agents have been implicated in the induction of autoimmune diseases, including sarcoidosis, with more than 30 cases of TNF-α antagonist-induced sarcoidosis reported." (PMID 22195005, 2011). "The pro-inflammatory properties associated with TNF-α play a major role in autoimmune diseases and interference with TNF- α production is a major treatment modality." (PMID 22194778, 2011). "Overproduction of TNFα is an underlying mechanism of autoimmune diseases, including RA, ankylosing spondylitis and psoriatic arthritis." (PMID 20140191, 2010). "In fact, many autoimmune diseases, such as rheumatoid arthritis, are associated with increases in TNF-α and IL-1β levels, and treatments that block these cytokines have proven beneficial in animal models and clinical settings." (PMID 15550215, 2004). "Our observation that the A allele of SNP rs1800629 in the TNF gene was more frequent in children with GN is in accordance with the fact that it is known to influence gene expression and is linked to various infectious and autoimmune diseases." (PMID 40725812, 2025). "Furthermore, when comparing with other autoimmune diseases, we found that the reduction of pro-inflammatory cytokines, including TNF-α, IL-1α, and IL-1β, is associated with decreases disease occurrence." (PMID 40206211, 2025). "Moreover, TNF-α has been implicated in the pathogenesis of numerous inflammatory and autoimmune disorders." (PMID 40430212, 2025). "Conversely, although anti-TNF antibody therapies have transformed the treatment of autoimmune diseases, changes in immune status caused by these TNF antibodies may unintentionally facilitate the development and progression of cancer." (PMID 39744497, 2025). "The proinflammatory cytokines IL-23, TNF-α, and IL-6, induced by S. copri-OMVs in monocyte-derived macrophages, are related to the generation of IL-17-secreting Th17 cells and a shift in the Th17/Treg balance—a hallmark of autoimmune diseases such as RA." (PMID 40332148, 2025). "TNF is a pleiotropic cytokine implicated in the regulation of cell proliferation, apoptosis, differentiation, coagulation, and lipid metabolism and is involved in a variety of diseases, including insulin resistance, carcinoma, and autoimmune diseases." (PMID 40725812, 2025). "Tumor necrosis factor-alpha (TNF-α) inhibitors are effective treatments for autoimmune diseases but may cause paradoxical adverse events (PAEs), including sarcoid-like granulomatosis." (PMID 41107632, 2025).
autoimmune disease (continued). "While TNF is essential for host defense and tissue homeostasis, its dysregulated or excessive production is implicated in the pathogenesis of various inflammatory and autoimmune diseases and also in MS within the CNS." (PMID 41373455, 2025). "In addition, serious side effects such as infections, malignancies, and autoimmune diseases are discussed as being associated with TNF blockers." (PMID 39093345, 2025). "However, excess production of TNF-α is linked to chronic inflammation and is implicated in the pathogenesis of several inflammatory and autoimmune diseases." (PMID 38984140, 2024). "Finally, we examined the expression of IFN-γ and TNF, pleiotropic cytokines that are instrumental in regulating immune response and also associated with autoimmune diseases." (PMID 39850904, 2024). "Given that HC users are at elevated risk of developing some autoimmune disorders compared to NC women, it is possible that this increased risk is mediated through biasing women’s cytokine response to stress toward one marked by elevated levels of TNF-α." (PMID 37914104, 2024). "Tumor necrosis factor (TNF) is one of the most potent pro-inflammatory cytokines that cause cell death and promote inflammatory responses, and high levels of TNF are attributable to the pathogenesis of autoimmune disease." (PMID 37662935, 2023). "Therefore, in this study, we performed a systematic review of data available over the last 25 years to clarify the risk of histoplasmosis as a complication of treatment with TNF-α inhibitors for autoimmune diseases." (PMID 38065857, 2023). "It has been suggested that susceptibility to autoimmune diseases may be directly related to polymorphisms in the TNF genes, such as TNF-α (-308G/A) gene and TNF-β (+ 252A/G)." (PMID 36802017, 2023). "In addition, TNF blockers have been associated with the development of autoimmune diseases, such as paradoxical psoriasis, demyelinating central nervous system disease, vasculitis, and lupus-like syndrome." (PMID 37176606, 2023). "This SNP, located at − 308 position with regard to the TNF promoter region, replaces guanine (G) with adenine (A), with the allelic types − 308 G/A, and has been linked to a variety of inflammatory condition and autoimmune diseases." (PMID 36622512, 2023). "Then again, anti-TNF therapy used for the treatment of other autoimmune diseases, such as RA or Crohn’s disease, seems to increase the risk of vasculitis development and, apart from a few successful reports, this type of therapy is not generally proposed for this group of patients." (PMID 37894997, 2023). "In human autoimmune disease models, overproduction of the IL-6 and TNF-α cytokines has been linked to develop spontaneous autoimmune diseases; this might be due to their potential to reduce the suppressive activity of Tregs." (PMID 37505830, 2023). "However, a recent nested case-control study showed that anti-TNF-α therapy exposure in patients with autoimmune diseases is associated with an increased risk of inflammatory central nervous system (CNS) events." (PMID 36389693, 2022). "Interestingly, the use of TNF antagonists as treatment for autoimmune diseases has been associated with an increased incidence of fungal infections." (PMID 36311802, 2022). "However, treatment with TNF inhibitors has been associated with aggravation of pre-existing autoimmune diseases and the onset of new inflammatory diseases and autoimmune phenomena." (PMID 36615129, 2022). "In addition, secondary antitumor necrosis factor α (anti-TNF α)-induced or anti-TNF α-associated ON has been reported in association with the wider use of anti-TNF α therapy for a variety of autoimmune diseases, including IBD and MS." (PMID 33578895, 2021). "However, the inappropriate or excessive activation of TNF-α signaling is associated with chronic inflammation and can eventually lead to the development of pathological complications such as autoimmune diseases." (PMID 33800290, 2021).
autoimmune disease (continued). "Underlying lung diseases, environmental exposures and toxins, autoimmune disease, long-term steroid therapy, use of immunosuppressive drugs such as TNF-alpha inhibitors may also predispose to histoplasmosis in children who are HIV-negative." (PMID 34209280, 2021). "Furthermore, the −308A allele has been associated with increased constitutive and inducible transcription levels and with increased production and secretion of TNF-α in patients with autoimmune diseases and healthy controls compared with the −308G allele." (PMID 34778454, 2021). "Furthermore, a class III TNF-α polymorphism is associated with a significant number of autoimmune diseases such as Sjögren’s syndrome, systemic lupus erythematosus, rheumatoid arthritis and ulcerative colitis." (PMID 34434197, 2021). "Activation of the TNF-α system is associated with activation of T-cells, which is evident with increase in serum levels of sIL2Rα, a marker for activated T-cells in several autoimmune diseases including T1D." (PMID 33868296, 2021). "Abnormal production of some cytokines such as tumour necrosis factor (TNF)-α, interleukin-1-beta (IL- 1β), soluble IL-2 receptor (sIL-2R), IL-6, and chemokine IL-8 have been implicated in the pathogenesis of various inflammatory and autoimmune diseases." (PMID 34403420, 2021). "In addition, activation of NKRP1A on T cells had been found to be associated with IL17, IFN-γ, and TNF production and is involved in the process of inflammation and the pathogenesis of autoimmune diseases." (PMID 34603038, 2021). "Recent investigations have also suggested that genetic alterations within the CD6 gene associated with clinical outcome of several autoimmune diseases and correlated with the response to TNFi, which pointed to a role of these soluble scavenger receptors in modulating response to anti-TNF drugs." (PMID 34777329, 2021). "Interestingly, the use of TNF-α inhibitors in autoimmune diseases seems to be associated with the increased risk of NMSCs occurrence, in particular." (PMID 33461943, 2021). "Autoimmune diseases may underlie the development of secondary IgA nephropathy associated with anti-TNFα therapy, and so further studies are needed to better understand the association between molecular-targeted drugs and IgA nephropathy." (PMID 32842976, 2020). "The present study used a nested case-control cohort matched by type of autoimmune disease, sex, and age and found that TNF inhibitor exposure appeared to be associated with these inflammatory CNS events (both demyelinating and nondemyelinating), beyond these baseline clinical characteristics." (PMID 32421186, 2020). "A number of autoimmune diseases are associated with an overexpression of TNF." (PMID 32093269, 2020). "Moreover, in the United States and other nations, patients with TNF-linked autoimmune diseases have been authorized to be treated with TNF blockers." (PMID 33087125, 2020). "Interestingly, these SNPs are associated with enhanced serum levels of TNFα and IFNα and also with autoimmune diseases of mucosal sites." (PMID 32328064, 2020). "Plaque psoriasis is an autoimmune disease characterized by skin lesions that can reduce the quality of life, and it is considered to be associated with inflammatory cytokines, such as tumor necrosis factor (TNF)-α, interleukin (IL)-17, and IL-23." (PMID 31654299, 2020). "Recent studies have shown that curcumin ameliorates autoimmune diseases by regulating inflammatory cytokines such as IL-1beta, IL-6, IL-12, TNF-alpha and IFN-gamma and associated JAK-STAT, AP-1, and NF-κB signaling pathways in immune cells, as reviewed by others." (PMID 32143311, 2020). "Indeed, persistently elevated levels of TNF-α have been showed in chronic inflammation and associated with a variety of autoimmune diseases." (PMID 30563131, 2018).
autoimmune disease (continued). "Previous studies showed that pro-inflammatory cytokines, particularly TNF-α disrupted the stability of regulatory T cells (Treg), which could even drive the pathogenic conversion of these cells in autoimmune diseases." (PMID 29628928, 2018). "However, at high levels, TNF-α is also implicated as the source of many inflammatory and autoimmune diseases and has been shown to cause severe tissue damage when it is overexpressed during an M. tuberculosis infection." (PMID 30126957, 2018). "In addition, TNF-α plays a pivotal role in a variety of autoimmune diseases, causing sustained inflammation and tissue damage." (PMID 30463908, 2018). "Indeed, persistently elevated levels of TNF have been implicated in chronic inflammation and have been associated with a variety of diseases including autoimmune diseases and neurodegenerative diseases." (PMID 25834699, 2015). "In addition, benfotiamine reduced expression and release of TNF-α and IL-6, which are the cytotoxic mediators linked with the development of chronic inflammatory and autoimmune diseases." (PMID 25695433, 2015). "Together, these data indicate that soluble CRT in oligomerized form could play a pathogenic role in autoimmune diseases through induction of pro-inflammatory cytokines (e.g., TNF-α and IL-6) by macrophages via MAPK-NFκB signaling pathway." (PMID 24566135, 2014). "TNF shows different physiologic and pathogenic effects in autoimmune diseases." (PMID 23702100, 2013). "Based on the preexisting evidence for the impact of TNFα in the pathogenesis of autoimmune disorders and their known association with an acquired hypercoagulability, we investigated the effects of TNFα and the role of the TNF receptor subtypes TNFR1 and TNFR2 for arteriolar thrombosis in vivo." (PMID 23079185, 2012). "The −308 and −238 single nucleotide polymorphisms (SNP) of TNF-α may influence the presence of autoimmune diseases and TB." (PMID 22482039, 2012). "However, primary role of TNF-α is in the regulation of immune cells and its overproduction has been implicated in a variety of human diseases including autoimmune disorders and cancer." (PMID 23284977, 2012). "TNF has been implicated in an array of diseases including autoimmune disease and cancer." (PMID 17081307, 2006). "TNFα is a pro-inflammatory cytokine that has been found at elevated levels in the serum of patients suffering SLE and other autoimmune diseases; it has also been suggested that TNFα genotype influences their susceptibility and, possibly, their clinical response to treatment." (PMID 16507146, 2006). "B cells exhibit dual immunomodulatory functions in T-cell-mediated autoimmune diseases, demonstrating both protective effects through regulatory cytokine secretion (e.g., IL-10) and pathogenic contributions via proinflammatory mediators (including TNF-α, IL-6, and GM-CSF)." (PMID 40691766, 2025). "However, excessive TNF production or activation may be associated with pathological conditions such as autoimmune diseases, chronic inflammatory conditions, and tissue damage." (PMID 39200293, 2024). "However, inappropriate or excessive activation of TNF-α signaling is associated with chronic inflammation, which, if persistent and unregulated in susceptible hosts, can exacerbate tissue injury in different inflammatory and autoimmune diseases." (PMID 39591258, 2024). "Similarly, anti-TNF therapeutics have been associated with severe side effects, such as exacerbated inflammation, opportunistic infections, reactivation of tuberculosis and the development of autoimmune disease." (PMID 37122019, 2023). "However, inappropriate or excessive activation of the TNF-α signaling pathway is associated with chronic inflammation, which may ultimately lead to the development of pathological complications, such as autoimmune diseases." (PMID 36293806, 2022).